FGFR1 (fibroblast growth factor receptor 1)
Diseases named in the same sentence as FGFR1 in open-access papers (continued):
Sharing a sentence is not in itself a finding about the gene and the disease.
tumor (continued). "We validate FGFR1 as a potential therapeutic target by showing that at least one FGFR1-amplified NSCLC tumor cell line is sensitive to FGFR enzymatic inhibition and dependent on FGFR1 expression for cell viability as evidenced by shRNA treatment." (PMID 21666749, 2011). "Patients with low FGFR1-expressing HNPC had a mean time to relapse of 3.9 years, whereas patients with tumours showing high cytoplasmic FGFR immunoreactivity relapsed quicker with a mean time to relapse of 2.1 years (P=0.006)." (PMID 21952621, 2011). "In our previous study, FGFR1 and FGFR2 expression was widely observed in both tumour cells and ECs of the human HNSCC xenograft model." (PMID 21063405, 2010). "In vivo, GEM inhibited tumor growth and downregulated HIF1A, UBR5, and FGFR1." (PMID 42318009, 2026). "Overexpression or abnormal splicing of FGFR1 can promote EMT, enhance invasion and metastasis ability, and drive cell proliferation through MAPK/ERK or COX-2 pathways, which is closely related to tumor malignancy progression." (PMID 41019085, 2025). "Combined inhibition of FGFR1 and MET significantly suppressed tumor growth in resistant cells." (PMID 41315241, 2025). "Given that the FGFR1::SLCO5A1 fusion was detected in the primary tumour but not in the metastatic focus, it is possible that this represents a random event rather than a pathogenic alteration." (PMID 40177273, 2025). "Regardless of the tumor type, the mutation frequencies of CD74, FGFR1, and RET were significantly greater in patients with NRG1 fusion than in patients without NRG1 fusion." (PMID 40730881, 2025). "BL tumor cells exhibited elevated expression of MGP (matrix Gla protein), AZGP1 (alpha-2-glycoprotein 1), AGR2 (anterior gradient protein 2), TFF3 (trefoil factor 3), and FGFR1 compared to EP and LP cells." (PMID 39955556, 2025). "By binding to FGFR1, FGF9 activated FAK, AKT and ERK/MAPK signaling pathways to promote tumor cell proliferation and epithelial-mesenchymal transformation (EMT), thereby enhancing tumor cell migration and invasion." (PMID 40526701, 2025). "Indeed, lenvatinib acts by inhibiting multiple receptor tyrosine kinases, including VEGFR1–3, FGFR1–4, PDGFRα, RET and KIT, thereby impairing angiogenesis and tumor proliferation." (PMID 40507289, 2025). "FGFR1 amplification triggers the PLCγ (phospholipase C gamma)/PKC (protein kinase C), RAS/MAPK (mitogen-activated protein kinase), and PI3K/AKT pathways, promoting angiogenesis as well as the growth and proliferation of tumor cells." (PMID 40083325, 2025). "PLXNA4 forms complexes with fibroblast growth factor receptor 1 (FGFR1) and vascular endothelial growth factor receptor 2 (VEGFR-2) to boost basic fibroblast growth factor (bFGF)/VEGF pathways, promoting proliferation and tumor growth." (PMID 41562091, 2025). "In addition to this, fibroblast growth factor receptor 1 (FGFR1) was found to be a key driver of gemcitabine resistance (GemR) and increased tumor aggressiveness." (PMID 40003950, 2025). "Moreover, miR-133a-3p can target multiple receptors, such as EGFR, FGFR1, IGF1R, and MET receptors, to inhibit tumor cells." (PMID 40170845, 2025). "None of the tumor tissues stained positive for FGFR1, whereas FGFR1 was consistently expressed in the smooth muscle surrounding blood vessels, Purkinje cells, and the cerebellar cortex." (PMID 40393028, 2025). "Furthermore, the gains on 8p11 encompassing FGFR1 and ZNF703 is the second most common hotspot in our analysis (#2), which agrees with previous tumor-related literature." (PMID 38473323, 2024). "There were two instances of the FGFR1 gene amplification and one tumor with FGFR4 gene extra copies; however, no increase in mRNA expression of the corresponding gene was observed in these samples." (PMID 39596194, 2024). "FGF2/FGFR1 induces resistance to radiotherapy in GBM, and inhibition of FGFR1 reduces radioresistance in GBM mouse xenografts, although tumor growth is not reduced by FGFR1 silencing alone without irradiation." (PMID 39682716, 2024).
tumor (continued). "Several previous studies showed tumor location was related to the survival of H3K27M‐DMG and the prognosis of patients with infratentorial tumor was poorer than those with supratentorial tumor as well as different molecular alterations such as PDGFRA and FGFR1 between brainstem and thalamus tumor." (PMID 38644565, 2024). "In addition, we identified the expression of fibroblast growth factor receptor 1 (FGFR1) and several FGF ligands in the embryonal tumor cluster." (PMID 39567475, 2024). "The patient was diagnosed with progressive disease 3 months after surgery and treated under the NCI-Children’s Oncology Group (COG) MATCH Study with Erdafitinib, an FGFR1 inhibitor, which initiated tumor response but was not tolerated by the patient." (PMID 38903142, 2024). "The unfavorable seizure outcome in FGFR1-mutant LEAT is presumably attributed to the presence of residual tumor, because of the larger volume of FGFR1-mutant LEAT than those of other genotypes, as well as the different biological natures of FGFR1-mutant tumors and other genotypes." (PMID 39081340, 2024). "Studies have shown that PD 173074 significantly reduces the phosphorylation levels of the MAPK pathway in non-small cell lung cancer (NSCLC) with FGFR1 amplification, subsequently reducing ERK phosphorylation, a member of the MAPK family, affecting tumor cell proliferation." (PMID 39590377, 2024). "Compared to patients with FGFR1 negative tumor-adjacent tissue, patients with FGFR1 positive tumor-adjacent tissue were more frequent >50 years at diagnosis." (PMID 37546410, 2023). "In addition, miR‐22 in vascular endothelial cells in NSCLC tissues directly targets sirtuin 1 and FGFR1, inactivating their common AKT/mTOR pathway to inhibit angiogenesis and tumor cell growth." (PMID 37750089, 2023). "All tumor samples shared the same genomic alteration of FGFR1 in DNET, regardless of the space (main tumor or SL) and time (primary or recurrence)." (PMID 36639714, 2023). "Since our in-vitro data suggested adding HS5-CM to MCL cells up-regulated FGFR1, we questioned a) whether stroma can promote MCL tumor progression in-vivo and b) if treatment with erdafitinib can abrogate stromal-mediated tumor progression in-vivo." (PMID 37598282, 2023). "The present studies demonstrate that targeting eIF4A by zotatifin can robustly inhibit the translation of Sox4 and Fgfr1 in TNBC GEM models, resulting in not only the inhibition of cell proliferation, but also the induction of IFN-related pathways and remodeling of the tumor immune microenvironment." (PMID 37874652, 2023). "It functions by inhibiting the growth of tumor cells and the formation of blood vessels through targeting various serine/threonine and tyrosine kinases such as RAF1, BRAF, VEGFR 1, 2, 3, PDGFR, KIT, FLT3, FGFR1, and RET." (PMID 37299411, 2023). "Concerning copy number aberrations (CNAs), the top amplified genes in the samples from the primary tumor were ERBB2 (6/19, 32%), AURKA, PPM1D (4/19, 21%), and FGFR1 (3/19, 16%), while in the metastatic samples ERBB2 (7/17, 41%), CDK12, FGFR1 (4/17, 24%), and AURKA, MDM4, MYC (3/17, 18%)." (PMID 36717329, 2023). "Therefore, we wanted to elucidate if FGFR1 and FGFR2 are expressed in GBM in vivo and if there are receptor-specific patterns of expression, specifically comparing tumor core and invasive areas." (PMID 37579831, 2023). "Assuming that the amplification of FGFR1 might describe a specific manner of tumor development in LSCC, it is likely that THSD7A positivity describes a different manner of tumor development." (PMID 37445817, 2023). "Decreased FGFR1 expression in shFGFR1 cells resulted in lower fluorescence intensity of FGFR1 staining in xenografted tumors, with no appreciable difference between tumor core and invasive edge." (PMID 37579831, 2023).
tumor (continued). "Thus, FGFR1 is expressed in both core and invasive areas of xenografted human GBM and FGFR2 is mainly expressed in the tumor core." (PMID 37579831, 2023). "The analysis of FGFR1 protein abundance in human MB tissues, through an anonymized, validated MB, and cerebellum tissue microarray (TMA) and immunohistochemistry (IHC) found high levels of FGFR1 expression in 18% of the tumor tissues." (PMID 36839989, 2023). "Altogether, our results hinted that DJ-1 plays vital roles in tumor microenvironment in HCC development, and DJ-1/FGFR1 signaling pathway may be a therapeutic target for overcoming sorafenib resistance in treating HCC patients at the late stage." (PMID 35770048, 2022). "In addition, we also analyzed tumor angiogenesis genes, and the results showed that seven tumor angiogenesis genes (HIF1A, PDGFB, NRP1, VEGFB, FGFR1, ROBO1, and SLIT1) had substantially higher expression in the high-risk group compared with the low-risk group." (PMID 35311113, 2022). "Furthermore, it has been recently described that glutaminolysis drives tumor angiogenesis by controlling endothelial growth factor receptor 2 (VEGFR2) and fibroblast growth factor receptor 1(FGFR1) translation via mTORC1 activation." (PMID 35681715, 2022). "Here, we demonstrated that bevacizumab treatment induced tumor hypoxia to upregulate the expression of FGFBP1 in tumor cells, which activated the FGF2/FGFR1 signaling pathway to promote HSCs’ transformation into multiple phenotypes, including an “immunogenic” phenotype." (PMID 35951441, 2022). "Tumours with low levels of FGFR4 showed the highest basal-like/squamous scores regardless of the FGFR1 status (either high or low); indeed, the signature scores between the FGFR4lowFGFR1high and FGFR4lowFGFR1low were not significantly different." (PMID 35963908, 2022). "The analysis revealed high correlation within FGFR1, FGFR2, and FGFR3 expression assessed with both methods (r = 0.77, p = 0.000001; r = 0.86, p = 0.000001; and r = 0.95, p = 0.000001, respectively) in 40 Sq-NSCLC tumor samples." (PMID 36142417, 2022). "Mechanistically, tumor cell–derived FGF-2 strongly promoted pericyte proliferation and pericyte-specific expression of an orphan chemokine (C-X-C motif) ligand 14 (CXCL14) via FGFR1/AHR signaling." (PMID 35439170, 2022). "They claimed that RAPGEF5 suppression could attenuate the transmembrane signaling receptor “fibroblast growth factor receptor 1 (FGFR1)” and thus suppress tumor growth by binding to miR-198, which sponged the 3′-UTR of FGFR1 via circRAPGEF5 targets in vitro." (PMID 36230649, 2022). "While relatively enriched in basal-like PDAC, the expression of FGFR1 did not significantly discriminate basal-like from classical tumours in the 3 PDAC cohorts investigated." (PMID 35963908, 2022). "Primary tumors had nonsignificantly lower FGFR1 IR scores (mean 4.8) compared to tumor recurrences (mean 5.7, p = 0.326)." (PMID 35018490, 2022). "In order to show that the anti-tumor effect of AZD4547 against KM12(Luc) is caused by inhibition of TRKs rather than FGFR, we monitored mRNA levels of FGFR1/2 and NTRK1/2 in KM12(Luc)." (PMID 34790577, 2021). "Considering the high expression levels of FGFR1 and FGFR3 across all EPN subtypes as well as the FGFR-driven malignant phenotype of ST-RELA and PF-A tumor cells, we tested the sensitivity of EPN cells towards a panel of small molecule FGFR tyrosine kinase inhibitors (FGFRi)." (PMID 34046693, 2021). "In contrast to UC tumor specimens, phosphorylation of members of the FGFR family of RTKs was lower in UC cell lines (FGFR1 25%, FGFR2 25%, FGFR3 25%, and FGFR4 0%) which may reflect the presence of stromal cells within the primary tumor samples evaluated." (PMID 34600548, 2021). "Dysregulation of HER2 or FGFR1/2 in human cancers leads to activation of the PI3K/AKT and RAS/ERK signaling pathways, thus enhancing eIF4A activity and promoting the translation of select oncogenes that are required for tumor cell growth and survival." (PMID 34900714, 2021).
tumor (continued). "This was confirmed by the lack of FGFR1 expression in tumor tissue sections treated with the FGFR1i-AuNSs." (PMID 33596850, 2021). "The pathways related to tumor progression, such as positive regulation of the MAPK cascade and FGFR (FGFR1, FGFR2, FGFR2c, FGFR3, and FGFR3c) ligand binding and activation, were significantly downregulated in the FSIP2-MT group (ES < 0, p < 0.05), suggesting a better efficacy." (PMID 34113648, 2021). "The tumor sample from one pazopanib‐responsive patient had alterations in FGFR1, KIT, and KDR, while the other had no alterations in genes associated with pazopanib activity." (PMID 34269527, 2021). "Although bFGF was upregulated both in tumor cells and tumor endothelial cells, expression of FGFR1 and FGFR2 was not affected in this model." (PMID 33804681, 2021). "Overexpression of FGFR1 promoted a significant increase in growth rate of HME2 tumors upon mammary fat pad engraftment, leading to differential TDM1 treatment initiation times for matched tumor sizes." (PMID 33479246, 2021). "The PDX GCRC1863, with low expression of FGFR1 and absence of Met and FGFR1 co-localisation in the tumour, was included to validate staining specificity." (PMID 33772015, 2021). "To evaluate whether FGFR1 upregulation occurs in clinical NSCLC tumors that progressed on EGFR-TKI treatment, we examined the FGFR1 mRNA expression in paired tumor samples from EGFR-mutant NSCLC patients at baseline and after progression to EGFR-TKI treatment." (PMID 34267282, 2021). "Furthermore, overexpression of FGF12, FGF14, FGF17, FGFR1, FGFBP3 and IGFBPL1 genes was found in early tumor stage, while, overexpression of IGF1R, IGF2BP2 and INSRR was found in advanced tumor stages." (PMID 34061869, 2021). "In parallel with mRNA assays, Western blot results showed that FGFR1 and PARP1 protein expression levels were 1.55- and 1.84-fold higher, respectively, in poorly differentiated FGFRi-resistant primary tumor PANC-1 cells than FGFRi-sensitive metastatic SUIT-2 cells." (PMID 32276472, 2020). "Recurrent alterations involving FGFR2/3 (rather than the more frequent FGFR1) have been identified in a recently defined tumor type, PLNTY, which carries a good prognosis." (PMID 32164789, 2020). "Immunohistochemistry for FGFR1 was performed on tumour tissue samples of patients #3 and #5, which revealed no apparent positivity in either of the tumour components (data not shown)." (PMID 32058674, 2020). "Moreover, we detected eight gene amplifications in six different tumor specimens, including CCND2 (n = 3), FLT3 (n = 3), FGFR1, and MYC." (PMID 33322358, 2020). "FGFR1 was also altered in the patient normal, tumor, and PDX tumor tissue for both PDX15 and PDX36." (PMID 32825052, 2020). "CGH/SNP-array analysis of the tumor showed that co-overexpression of FGFR1 and FGFR4 did not result from FGFR gene amplification." (PMID 33092134, 2020). "In contrast, 3D185 was inactive against 20 additional tumor cell lines that exhibited low expression or activation of FGFR and CSF-1R (IC50 > 1 μM), further demonstrating that 3D185 is a highly potent and selective FGFR1/2/3 and CSF-1R inhibitor." (PMID 31438996, 2019). "This percentage increased for FGFR1‐15R and FGFR1‐25Ra 30 min after FGF‐2‐treatment as compared with FGFR1‐WT confirming previous data on enhanced recycling capabilities of FGFR1‐15R and FGFR1‐25Ra in tumor cells." (PMID 30950230, 2019). "We further traced the fractional contributions of glucose and lactate to the TCA cycle in FGFR1 amplified NCI-H1581 xenograft model, in which mice were co-injected with [U-13C6]-glucose and [3-13C]-lactate intravenously and tumor tissues were collected after 30 min." (PMID 31221965, 2019). "Reports from other cancer types targeted with FGFR1 inhibitors support the notion that inhibitors do not have equivalent efficiency varying from one tumor type and drug family to another suggesting the FGFR alterations have different biological meanings." (PMID 30931252, 2019).
tumor (continued). "FGFR1 fluorescent in situ hybridization (FISH) was evaluated and high-level amplification was defined as a ratio of FGFR1 to the centromere 8 (CEN8) marker of ≥2 or a defined number of tumor cells with various levels of FGFR1." (PMID 29351293, 2018). "The combination of FGFR inhibitors with agents targeting AKT/mTOR signaling pathway increases the anti-tumor effects induced by FGFR inhibition; this drug combination could represent a new therapeutic strategy for FGFR1-amplified LSQCCs." (PMID 30060526, 2018). "This suggests that the inhibitory effect of honokiol on tumor xenograft growth may be related to the downregulation of FGF2 and the inhibition of FGFR1." (PMID 30515999, 2018). "These genetic alterations involving BRAF, KRAS, RAF1, NF1, FGFR1, and FGFR2 were mutually exclusive (i.e. no tumor harbored any two of these variants simultaneously)." (PMID 29880043, 2018). "This study summarizes the relationship between the circulating tumor cell (CTC) in peripheral blood, expression of fibroblast growth factor receptor 1 (FGFR1) and clinic pathological features in 30 patients with NSCLC so as to provide new ideas for the detection of tumor recurrence and metastasis." (PMID 29764586, 2018). "FGFR1–3 were broadly expressed across tumour and glial cells and not differentially expressed between compartments [Suppl." (PMID 29541918, 2018). "Although BGJ398 enhanced the anti-tumor effect of PTX, it is unclear whether the synergistic effect of PTX and BGJ398 is mainly derived from the inhibition of FGFR1 or its other target molecules." (PMID 30326563, 2018). "Another important finding was that miR-497, known as a tumor suppressor, directly targeted the 3′-UTR of FGFR1 to inhibit the process of translation, which is a classical post-transcriptional mechanism involved in cell growth inhibition and apoptosis in AGS and SGC-7901 cells." (PMID 30484492, 2018). "Moreover, our analysis identifies consistent cross-cancer effects for 4 genes (FGFR1, ERRB2, IDH1, KRAS/NRAS) in 14 tumor types." (PMID 30442178, 2018). "Moreover, our analysis identifies consistent cross-cancer effects for 4 genes (FGFR1, ERRB2, IDH1, KRAS/NRAS) in 11 histological tumor types." (PMID 30442178, 2018). "As a consequence of the anti-FGF2/anti-angiogenic activity of PTX3, FGF2-dependent syngeneic tumor grafts of different origin were characterized by impaired FGFR1 activation and reduced CD31+ vascularization and tumor growth when injected in TgN(Tie2-hPTX3) mice." (PMID 30349543, 2018). "Additionally, VE-Cadherin and FGFR1 levels were reduced in DCKO tumors compared to control tumors, reflective of reduced tumor angiogenesis and tumor endothelial Fgfr1 deletion." (PMID 30283071, 2018). "The level of FGFR1 amplification did not correlate with tumor stage, lymph node staging, or metastasis." (PMID 29351293, 2018). "We previously observed that NSCLC with amplification of FGFR1 were not dependent on E2 for release of FGFs and showed no increased anti-tumor effects when FGFR inhibitors were combined with fulvestrant (unpublished observations)." (PMID 28445992, 2017). "Expression of both FGFR1 and FGFR3 varied within all tumor types." (PMID 28468611, 2017). "Also IBC tumor samples showed amplifications in the following: MYC (8/32; 25%), CCND1 (7/32; 22%), ErbB2 (5/32; 16%), MCL1 (6/32; 19%), and FGFR1 (3/32; 9%)." (PMID 28271309, 2017). "Anlotinib, a broad-spectrum anti-tumor drug designed to primarily inhibit VEGFR2/3, FGFR1-4, PDGFR α/β, c-Kit, and Ret, has shown manageable toxicity, long circulation, and anti-tumor potential in patients with advanced refractory solid tumors in phase I clinical trials." (PMID 28629427, 2017). "Given that miR-361-5p downregulated FGFR1 and MMP-1 in BC cells to suppress tumor progression, we next explored whether this relationship existed in clinical samples." (PMID 29132384, 2017).